FASTKD1 (FAST kinase domains 1)
Description:
Involved in the down-regulation of mitochondrial MT-ND3 mRNA levels which leads to decreased respiratory complex I abundance and activity.
Synonyms: FLJ21901
Tractability: PROTAC: ubiquitination databases record sites on it; its protein half-life has been measured.
Gene: Protein-coding gene on chromosome 2 (169,528,508 to 169,573,912, reverse strand). Ensembl gene ENSG00000138399.
Subcellular location: Mitochondrion
Subcellular location (Human Protein Atlas): Mitochondria; Nucleoplasm
Gene Ontology:
Molecular function: protein binding; RNA binding
Biological process: mitochondrial RNA metabolic process; regulation of mitochondrial mRNA stability; mitochondrial RNA processing
Cellular component: mitochondrion; mitochondrial matrix; ribonucleoprotein granule
Genetic constraint (gnomAD): Loss-of-function variants: 43 observed, 55.01 expected, observed/expected ratio (o/e) 0.78, 90% interval 0.61 to 1.01. The upper end of that interval is the gene's LOEUF score, 1.01, which puts it in group 4 of 6, group 1 being the genes least tolerant of losing a copy. Missense variants: 638 observed, 704.54 expected, observed/expected ratio (o/e) 0.91, 90% interval 0.85 to 0.97. Synonymous variants: 229 observed, 243.71 expected, observed/expected ratio (o/e) 0.94, 90% interval 0.84 to 1.05.
Homologues: Orthologues: chimpanzee FASTKD1 (99% identical), macaque FASTKD1 (90% identical), rabbit FASTKD1 (74% identical), dog FASTKD1 (74% identical), pig FASTKD1 (72% identical), mouse Fastkd1 (67% identical), rat Fastkd1 (64% identical), guinea pig FASTKD1 (51% identical), tropical clawed frog fastkd1 (46% identical), zebrafish fastkd1 (45% identical), Drosophila melanogaster CG31643 (19% identical). Paralogues in human: FASTKD3 (15% identical), TBRG4 (13% identical), FASTKD2 (13% identical), FASTKD5 (12% identical), FASTK (10% identical).
Diseases named in the same sentence as FASTKD1 in open-access papers:
FASTKD1 is named in the same sentence as 6 diseases in open-access papers, as found by Europe PMC text mining. Sharing a sentence is not in itself a finding about the gene and the disease. The quoted sentences say what the papers report.
endometrial tumors (1 paper, 2021). "FASTKD1 could also be used as a biomarker of primary endometrial tumors." (PMID 34976013, 2021).
multiple myeloma (1 paper, 2021). "In our study, we found for the first time that FASTKD1 and SNRPD3 are related to the prognosis of multiple myeloma, and the specific function and mechanism of these genes in tumorigenesis in multiple myeloma require further study." (PMID 34976013, 2021). "The risk score was also negatively correlated with the expression of immune checkpoints, indicating that ADAR, FASTKD1 and SNRPD3 might interact with the immune microenvironment of multiple myeloma." (PMID 34976013, 2021).
myocardial infarction (1 paper, 2022). Gross necrosis of the myocardium, as a result of interruption of the blood supply to the area, as in coronary thrombosis. "Owing to this function, FASTKD1 was considered as a novel target for modulation of oxidative stress induced cell death and post-myocardial infarction healing.Apart from this, FASTKD1 is considered as an early precursor of hematopoietic cells." (PMID 36518140, 2022).
cancer (1 paper, 2021). A tumor composed of atypical neoplastic, often pleomorphic cells that invade other tissues. "FASTKD1, FASTKD3 and FASTKD5 were the FASTK genes most frequently mutated in cancers." (PMID 34768773, 2021). "As reviewed in the introduction, several studies have previously reported upregulation of FASTK, FASTKD1, FASTKD2 and FASTKD3 in certain types of cancer." (PMID 34768773, 2021).
FASTKD1 also shares sentences with these, for which no sentence is quoted: breast carcinoma (1 paper); tumour (1).